LINC01393 (long independently transcribed non-coding RNA 1393)
Gene: Long non-coding RNA gene on chromosome 7 (115,030,564 to 115,126,314, forward strand). Ensembl gene ENSG00000225535.
Diseases named in the same sentence as LINC01393 in open-access papers:
LINC01393 is named in the same sentence as 3 diseases in open-access papers, as found by Europe PMC text mining. Sharing a sentence is not in itself a finding about the gene and the disease. The quoted sentences say what the papers report.
glioma (2 papers, 2023 to 2024). A benign or malignant brain and spinal cord tumor that arises from glial cells (astrocytes, oligodendrocytes, ependymal cells). "In glioma, the long non-coding RNA LINC01393 promotes the malignant biological behavior of tumors by regulating the miR-128-3p/NUSAP1 axis." (PMID 38441732, 2024). "A poor prognosis of glioma was significantly correlated with overexpression of LINC01393 according to the TCGA database." (PMID 36982952, 2023). "qPCR analysis of mice glioma specimens confirmed that NUSAP1 expression was indeed downregulated with the decrease of LINC01393." (PMID 36982952, 2023).
glioblastoma (1 paper, 2025). The most malignant astrocytic tumor (WHO grade IV). "LINC01393 promotes the occurrence and development of Glioblastoma by up-regulating NUSAP1 as a ceRNA of miRNA-128-3p and activating the NF-κB pathway." (PMID 40535133, 2025).
tumor (1 paper, 2023). "In vivo, LINC01393-knockdown decreased tumor growth and improved mice survival, while restoration of NUSAP1 partially reversed these effects." (PMID 36982952, 2023). "Brain MRI at 16 days and H&E staining of the tumors showed that tumor volume in the LINC01393-KD+NC group was significantly smaller than that in the NC group and the LINC01393-KD+NUSAP1-OE group." (PMID 36982952, 2023). "To examine LINC01393’s potential role in GBM cells migration and invasion, we conducted transwell cell migration and Matrigel-coated invasion assays and found that LINC01393-KD dramatically attenuated the tumor cell migration and invasion ability compared with NC." (PMID 36982952, 2023).